HMGB1 (high mobility group box 1)
Diseases named in the same sentence as HMGB1 in open-access papers (continued):
Sharing a sentence is not in itself a finding about the gene and the disease.
cancer (continued). "HMGB1 is passively released from dead or injured cells and actively secreted from immune cells and cancer cells in response to cellular stress signals." (PMID 24723911, 2014). "HMGB1 overexpression and cytoplasmic localization have been observed in some cancer cells such as in colon cancer, gastrointestinal stromal tumors, cervical carcinomas and melanoma." (PMID 25356587, 2014). "Measles virus (MV) causes ICD in human melanoma cells, because inflammatory cytokines and HMGB1 are released, and DCs are activated by MV-infected cancer cells." (PMID 24782985, 2014). "Understanding HMGB1-dependent and -independent autophagy in more detail will provide insight into the integrated stress response and guide HMGB1-based therapeutic intervention in cancer and other diseases." (PMID 25126737, 2014). "This led us to expand our investigation of HMGB1's regulatory abilities on cancer cell motility and metastasis." (PMID 25277185, 2014). "Reducible HMGB1 decreased cell death in cancer cells, whereas oxidized HMGB1 activated the mitochondrial apoptosis pathway." (PMID 25210949, 2014). "Our current study demonstrated a novel mechanism of HMGB1 in the regulation of cancer cell actin polymerization, cell skeleton formation, cancer cell motility and metastasis." (PMID 25277185, 2014). "Consistently, the effect of HMGB1 in the regulation of cancer cell migration, as well as invasion, was extended in transwell cell migration assay." (PMID 25277185, 2014). "Anti-HMGB1 neutralizing antibody significantly reduced the effect of extracellular HMGB1 released from dying cancer cells or of recombinant HMGB1 on Dox resistance." (PMID 25512109, 2014). "The ability of released HMGB1 to trigger drug resistance in cancer cells is reportedly due to autophagy." (PMID 25512109, 2014). "We further tested BP1 peptide which has both anticancer properties (it inhibits growth of cancer cells) and acts as an antiangiogenic (by inhibiting angiogenesis activated by HMGB1)." (PMID 24487722, 2014). "HMGB1 has been ascribed a dual role in cancer development and therapy, promoting cell survival as well as death by interfering with multiple signaling pathways, e.g. in inflammation, proliferation, apoptosis, autophagy and metastasis." (PMID 24705787, 2014). "Here we report that radiation induces cardinal signs of ICD (cell death and release of ATP and HMGB1) in multiple carcinoma types." (PMID 24480782, 2014). "Cancer cells that have undergone necrotic cell death can release Hmgb1 into the local microenvironment." (PMID 24453427, 2013). "In conclusion, our data revealed that the expression levels of HMGB1 and HMGB2 were highly increased in BCa, and that HMGB1/HMGB2 overexpression was significantly correlated with malignant tumor progression and angiogenesis." (PMID 23426143, 2013). "At later stages, other DAMPs such as HMGB1 are released from dying cancer cells and secreted from activated infiltrated immune cells." (PMID 24020520, 2013). "HMGB1-specific silencing also significantly decreased cell proliferation and sensitized cells to oxaliplatin-induced apoptosis mediated via the caspase-3 pathway, rendering HMGB1 a promising target structure in cancer therapy." (PMID 23378947, 2013). "HMGB1, the focus of many recent cancer studies, plays a critical role in cancer development, progression, and metastasis through its pro-angiogenic and pro-lymphangiogenic functions." (PMID 23866030, 2013). "Recent evidences strongly suggest that high mobility group box 1 (HMGB1) plays a pivotal role in the development of several cancer types including PCa." (PMID 23766911, 2013). "Previous studies have reported that pain-related behaviors in several preclinical models of chronic pain, including diabetic, cancer and neuropathic pain, were significantly attenuated by treatment with anti-HMGB1 antibody." (PMID 23991202, 2013).
cancer (continued). "Collectively these studies attest to the therapeutic utility of anti-HMGB1 antibody for cancer treatment in general, which can also be developed for PCa treatment." (PMID 23766911, 2013). "Specifically, this study revealed that HMGB1 expression correlated with stage of cancer (pT), Gleason grade, preoperative prostate specific antigen, biochemical recurrence, and poor survival rates." (PMID 23766911, 2013). "A follow-up study also demonstrated that HMGB1 antigenic peptides can act as an adjuvant for subunit cancer vaccines." (PMID 23766911, 2013). "Although there has been extensive characterization of the various roles of HMGB1 in cancer, considerably less is known regarding the involvement of HMGB2 in carcinogenesis, including its angiogenic effects and precise signaling pathways." (PMID 23426143, 2013). "As for the release of DAMPs from dying cancer cells, we first reported that cancer cells infected by an oncolytic virus, led to necrotic/apoptotic death pathways and HMGB1 was released into the extracellular milieu." (PMID 24020520, 2013). "When HMGB1 and CEA are combined, the overall diagnostic sensitivity is improved when compared to CEA alone (42% versus 25.6%) and the stage 1 cancer diagnosis (47% versus 5.9%)." (PMID 23586059, 2013). "HMGB1 has been identified to be a latent pro-angiogenic factor in cancer progression and angiogenesis; it has been observed to initiate the production of angiogenic factors, such as vascular endothelial growth factor (VEGF)." (PMID 23426143, 2013). "As it turns out, HMGB1 release is a universal phenomenon for OVs, as shown in cancer cells infected with an Ad, a measles virus, an HSV-2, and a coxsackievirus B3." (PMID 24020520, 2013). "When HMGB1 and CEA levels were compared, HMGB1 had similar efficacy as CEA regarding cancer detection (the sensitivity was 20.1% for HMGB1 vs. 25.6% for CEA, and the specificity was 96% for HMGB1 vs. 90.7% for CEA)." (PMID 22496788, 2012). "The secreted serum HMGB1 is expected to be derived from cancer cells or immune cells in the peritumoral area." (PMID 22496788, 2012). "All of these results suggest that HMGB1 is an important mediator for cancer transformation, cancer growth, and invasion." (PMID 22496788, 2012). "Although HMGB1 plays important roles in immune cells and cancer cells, differences exist in the biologic roles of HMGB1 between cancer and immune cells." (PMID 22496788, 2012). "Knockdown of HMGB1 or inhibition of its release leads to predominantly apoptosis and decreased autophagy in stressed cancer cells." (PMID 22629429, 2012). "We previously demonstrated that HMGB1 is translocated to the cytoplasm and secreted by cancer cells." (PMID 22496788, 2012). "RKO cell line among the cancer cells showed very low secretion of HMGB1 and this result corresponds to our previous result." (PMID 22496788, 2012). "Both GA and GL are known to directly interact with HMGB1 and inhibit its inflammatory actions in leukocyte chemotaxis, cancer, and post-ischemic liver and brain." (PMID 22824385, 2012). "HMGB1 has known to have diverse functions in cancer including anti-apoptosis, cell-cycle progression, cell growth, invasion, migration, and metastasis." (PMID 22496788, 2012). "A relationship has been suggested between HMGB1 and cancer based on findings that HMGB1 regulates the transcription of many cancer genes, such as E-selectin, TNF-α, insulin receptor, and BRCA1." (PMID 22496788, 2012). "Positive HMGB1 immunostaining was predominantly observed in the cytoplasm of carcinoma cell, and rarely in nucleus." (PMID 22747650, 2012). "For example, the transcriptional regulatory molecule high-mobility group B1 (HMGB1) was recently shown to regulate cancer-cell tumorigenesis, expansion, and invasion." (PMID 21915291, 2011).
cancer (continued). "Of note, CPT-11, modulated the high mobility group box-1 pathway, confirming the central role that it plays in the induction of anti-cancer activity by chemotherapeutics through activation of innate immunity." (PMID 21569348, 2011). "HMGB1 is a multi-functional protein that accelerates cell growth, invasion, and angiogenesis in cancer tissues, induces apoptosis in macrophages, and promotes immune responses." (PMID 20846416, 2010). "But the increased expression of HMGB1 protein was found in cancer samples, compared with the borderline and normal (distant) tissues." (PMID 20579387, 2010). "HMGB1-RAGE interactions have been found to be important in a number of cancers, which involves the MAPK/ERK pathway." (PMID 20579387, 2010). "We have developed a rule-based model of crosstalk between the HMGB1 signaling pathway and other key cancer signaling pathways." (PMID 21106117, 2010). "There was significant difference in cancer-free survival between groups with HMGB1 overexpression and with its low-level expression (P = 0.023)." (PMID 20579387, 2010). "Of course, the main stream of the study on HMGB1 is that it has the positive correlation with the occurrence, progression, and metastasis of cancers." (PMID 20579387, 2010). "More importantly, the co-expression pattern of nuclear and cytoplasmic HMGB1 in cancer cells was inversely related to the infiltration of CD3+ or CD45RO+ T cells and patient 5-year survival rate." (PMID 20846416, 2010). "HMGB1 plays a role in many clinical conditions such as autoimmunity, acute ischemia-reperfusion injury, cardiovascular disease and cancer." (PMID 20579387, 2010). "High mobility group box-1 (HMGB1) is a newly recognized factor regulating cancer cell tumorigenesis, expansion and invasion." (PMID 19476625, 2009). "In contrast to CEA, the sensitivity and specificity of serum HMGB1 levels for the diagnosis of cancer (EGC) was 67% and 71% (cut-off value of 5.5 ng/ml), and 71% and 67% (cut-off value of 5 ng/ml)." (PMID 19476625, 2009). "HMGB1 plays opposite roles in cancer development and treatment." (PMID 41296391, 2025). "In some cases, HMGB1 does promote cancer progression and invasion." (PMID 40969278, 2025). "Recent studies have shown that HMGB1 is overexpressed in a variety of cancers, including CRC." (PMID 40975711, 2025). "HMGB1 appears to have conflicting functions in the progression and treatment of cancer." (PMID 40495163, 2025). "Reduced levels of expression or activity of HMGB1 in cancer cells may result in an unfavorable disease course due to increased levels of genomic instability." (PMID 40804938, 2025). "Also, HMGB1 is capable of promoting activation and releasing processes of intratumoral T cells, which in return recruit waves of cancer-inducing macrophages." (PMID 41009692, 2025). "This study aimed to determine if HMGB1 would be released from human-derived cancer cells and normal cells after 131I-MIBG administration, with the goal of establishing useful radioimmunotherapy in the form of immunotherapy combined with 131I-MIBG, which has rarely been studied." (PMID 40583575, 2025). "Similarly, its cytoskeletal role via MST1/DOCK8/WASP expands upon HMGB1’s known capacity to modulate cell migration in cancer and endothelial cells." (PMID 40985892, 2025). "One study identified N6F11 as a selective ferroptosis inducer that degrades GPX4 specifically in cancer cells without affecting immune cells, thereby triggering ferroptosis in cancer cells and initiating HMGB1-dependent antitumor immunity mediated by CD8+ T cells." (PMID 40733146, 2025).
cancer (continued). "Moreover, a recent study with multiple cancer cell lines confirmed that HMGB1 release for ICD requires caspase activation, illustrating the striking ambivalence of cell death-related processes." (PMID 41304887, 2025). "MSCs treated with oxidized HMGB1 also increase cancer cell stemness and promote metastasis." (PMID 39940960, 2025). "HMGB1 has been demonstrated to be released from necrotic cancer cells into the microenvironment." (PMID 41009692, 2025). "Therefore, our in vitro experiments were conducted to determine the amount of increased HMGB1 released from only cancer cells and normal cells." (PMID 40583575, 2025). "As HMGB1-ferroptosis axis continues to expand mechanistically, further investigations are required to resolve the determinants and identify biomarkers of its pro- and anti-ferroptotic functions, as well as determine specific HMGB1 modulation to overcome therapy resistance in refractory cancers." (PMID 41465435, 2025). "However, the specific impact of EGCG-mediated HMGB1 inhibition in the context of reversing established cancer therapy resistance remains largely unexplored, presenting a compelling avenue for future investigation." (PMID 41465435, 2025). "In addition, external irradiation of cancer has been shown to damage cells and increase the release of HMGB1." (PMID 40583575, 2025). "Accordingly, these studies suggest that HMGB1 inhibition may be a promising approach to overcome key mechanisms of resistance to chemo- and immunotherapies in specific cancer contexts." (PMID 41465435, 2025). "Therefore, how to maintain the immune-stimulating, damage-repairing function of HMGB1 in cancer development is an important current challenge." (PMID 40969278, 2025). "Of 11,808 evaluable cancers, only 7.8% showed complete absence of HMGB1 staining (HMGB1 deficiency) while 9.9% showed 1+, 25.0% showed 2+, and 57.2% showed 3+ HMGB1 positivity." (PMID 40804938, 2025). "Moreover, extracellular HMGB1 can increase PD-L1 expression in cancer cells through the activation of the PI3K-AKT pathway after binding to RAGE, thus boosting migration and invasion." (PMID 40389855, 2025). "Our findings suggest that the HMGB1-targeted approach, which specifically inhibits the nucleo-cytoplasmic translocation of HMGB1, could provide an innovative therapeutic avenue in cancer treatment." (PMID 40389855, 2025). "The exact mechanisms by which HMGB1 exerts its effects in cancer remain to be fully elucidated." (PMID 41354099, 2025). "The role of HMGB1 in cancer is complex and not well understood." (PMID 40804938, 2025). "HMGB1 plays an important role in the development and progression of many cancers." (PMID 40969278, 2025). "Interestingly, recent reports have shown high expression of HMGB1 in cancer tissues compared to that in adjacent tissues and high serum levels of HMGB1 in cancer patients with metastasis." (PMID 40244228, 2025). "While external irradiation of cancer cells increases HMGB1 release, it remains unclear whether internal radiotherapy with 131I-meta-iodobenzylguanidine (131I-MIBG) induces similar effects." (PMID 40583575, 2025). "Additionally, GLO-1 expression demonstrated strong associations with both inhibitory and stimulatory ICPs, such as CD276, VEGFA, and HMGB1, across a majority of the analyzed cancer tissues." (PMID 40727469, 2025). "High-mobility group box 1 (HMGB1) is known to modulate cancer immunity." (PMID 39853458, 2025). "More importantly, the HMGB1/TLR4 pathway has multiple effects on cancer proliferation and invasion." (PMID 41296391, 2025). "A deeper understanding of HMGB1-mediated resistance mechanisms may offer new avenues for overcoming therapeutic resistance and improving clinical prognosis in cancer patients." (PMID 40969278, 2025).
cancer (continued). "Additionally, after vincristine, a medication that targets the microtubules, was administered to gastric cancer cells, HMGB1 was released into the extracellular space to prevent cancer cells from dying by inducing the transcription of Mcl-1." (PMID 41151762, 2025). "Collectively, cytosolic HMGB1 acts as a dynamic regulator of pro-survival autophagy in cancer cells exposed to anti-cancer therapies, which may represent a promising vulnerability to restore cancer sensitivity to treatment." (PMID 41465435, 2025). "When cancer cells die, they release high mobility group box 1 (HMGB1) into the TME, which activates the innate immune system by interacting with several pattern recognition receptors (PRRs), such as Toll-like receptors 2 and 4 (TLR2, TLR4) and the receptor for advanced glycation end products (RAGE)." (PMID 41153383, 2025). "Additionally, we found that HMGB1 protein was significantly upregulated after stimulation of ipNF95.6 cells with cancer cell supernatants after hypoxia incubation." (PMID 40148311, 2025). "The release of HMGB1 from damaged cancer cells may lead to improved cancer treatment, but HMGB1 released from damaged normal cells may contribute to or cause side effects." (PMID 40583575, 2025). "The stimulation of the TLR4 and RAGE signaling pathways by HMGB1 may promote cancer invasion and metastasis via caspase-1 activation and a cascade of inflammatory responses." (PMID 40331953, 2025). "C8 counteracts HMGB1’s effects and improves cancer-related myocardial damage." (PMID 39125651, 2024). "Additionally, infiltrating leukocytes and cancer cells can secrete HMGB1 in response to hypoxia, injury, inflammatory stimuli, or environmental factors." (PMID 38326739, 2024). "Taken together, this study proposes that HMGB1-structred RNA interaction in cancer cells is highly selective for rRNA modification, which may be integrated with HMGB1-promoted rRNA levels to increase protein synthesis in cancer cells." (PMID 38580917, 2024). "Nevertheless, it remains unclear how HMGB1 control ribosome biogenesis, and whether this control is related its regulation of cancer cell growth and apoptosis." (PMID 38580917, 2024). "We also demonstrated RAGE expression in cancer cells, which may indicate that HMGB1-RAGE-NF-κB signaling pathway is activated also in cancer cells." (PMID 39150932, 2024). "Notably, FBP has been identified as a novel HMGB1 ligand and holds potential as an HMGB1-targeted cancer therapeutic." (PMID 39693295, 2024). "In cancer cells, HMGB1 acts mainly through two signaling pathways." (PMID 38577597, 2024). "As HMGB1 and ATP released from cancer cells have been shown to cooperatively promote the activation of dendritic cells in oncolytic virotherapy, combination therapy may induce more profound ICD than monotherapy." (PMID 39108499, 2024). "Clinical applications of HMGB1 in cancer need further in-depth studies." (PMID 37897664, 2024). "g., high-mobility group box 1 (HMGB1)] following tissue damage or cancer treatment." (PMID 38327187, 2024). "Importantly, skeletal muscle atrophy has been observed to correlate with blood HMGB1 concentrations in human cancer cachexia cases." (PMID 38731953, 2024). "As both fatty acid synthesis and HMGB1 participate in cancer development, we embarked on investigating the mechanistic underpinnings of the relationship between lipid metabolism, immune regulation, and its potential impact on cancer therapy." (PMID 39100092, 2024). "Importantly, PRKN antitumor immunity was therapeutically actionable, and a clinically approved demethylating therapy with decitabine restored epigenetically silenced endogenous PRKN expression in cancer and enabled HMGB1-dependent IFN gene expression." (PMID 39213189, 2024). "Similarly, it has been verified that CAFs exhibit elevated levels of pro-inflammatory factors and can secrete signaling molecules (e.g., IL-8 and HMGB1) that activate the NF-κB pathway in neighboring cancer cells." (PMID 38649701, 2024).